TCF4 (transcription factor 4)
Diseases named in the same sentence as TCF4 in open-access papers (continued):
Sharing a sentence is not in itself a finding about the gene and the disease.
tumor (continued). "Given that TCF4 is a transcription factor and studies have shown that many regulatory feed-forward loops are involved in tumor progression 14, we tested whether TCF4 could regulate the expression of LncCCAT1." (PMID 31695775, 2019). "Silence of TCF-4 in LLC cells significantly decreased the tumor lesions in the lungs, while additional overexpression of MMP-15 could rescued this effect." (PMID 27046058, 2016). "TCF4 knockdown promoted HepG-2 cell differentiation and inhibited tumor formation, and TCF4 could be the potential downstream target for clopidogrel therapy." (PMID 27542264, 2016). "In fact, Tcf4 might represent a tumor suppressor as previously suggested by studies with Tcf4 knockout animals that developed hyperproliferation in the colon." (PMID 27811361, 2016). "The TCF4 induced ZEB1 was also shown to be related to tumor invasiveness due to its effects in EMT." (PMID 25299301, 2014). "Recent studies reveal that HIF-αs interact with β-catenin and, therefore, may regulate TCF-4-driven gene expression not only in stem/progenitors but also tumor cells experiencing hypoxic conditions during rapid growth." (PMID 22768190, 2012). "However, a tumour-suppressor role of plakoglobin has also been suggested because it can bind the transcriptional activator TCF-4 and thereby inhibit transcription of Wnt/β-catenin-responsive genes." (PMID 22333708, 2012). "This is consistent with our in vitro observations that sFZD7 inhibited β-catenin/Tcf4 mediated transcriptional activity, which might contribute to the observed tumor growth inhibition by sFZD7, and its chemosensitizing effect with Doxil." (PMID 21314951, 2011). "Moreover, Wnt signalling activity should also be examined in the tumour specimens to investigate the effect of Wnt activity on the expression and prognostic significance of Tcf-4 and OPN." (PMID 21772333, 2011). "Also, significant alterations in genes associated with tumor cell invasion were detected, such as significant upregulation of TGFβ1, ROAR, DAB2, BMP6, NOS2, PLXN2, and CADPS exhibited, and significant downregulation of TCF4." (PMID 38003292, 2023). "Moreover, AhR deficiency inhibited, rather than enhanced, tumor formation and tumor-derived organoids in Apc-deficient cells both in vivo and in vitro by activating Wnt/β-catenin signaling and TCF4/LEF1-dependent transcription." (PMID 37781044, 2023). "Therefore, TCF4 may be one of the important nodes for tumor cells to regulate ER stress and maintain protein synthesis homeostasis." (PMID 37337284, 2023). "Also, individual knockdown of β-catenin, TCF4, or p68 in Wnt3a-MCF7 cells using respective siRNAs showed that knockdown of any of these molecules resulted in reduced number of colonies, indicating that the tumour-promoting ability of β-catenin not only depends on TCF4 but also on p68." (PMID 25499975, 2014). "As LEF-1 has been shown to be a target of TCF4/β-catenin, we speculated that tumour progression may be accompanied by a shift of β-catenin binding partners from TCF4 to LEF1 and we therefore expected to find TCF4 positivity mainly in central tumour areas and LEF-1 mainly in the front of invasion." (PMID 21092222, 2010). "This increases the expression of TCF4 and DNMT1 and inhibits FAT4 expression levels (a protein that acts as a tumor suppressor) or promotes the nuclear translocation of β-catenin, where it activates the Wnt signaling." (PMID 41181715, 2025). "Our study reveals that the role of ALOXE3 as a tumor suppressor can trigger ferroptosis and the TRIB3-β-catenin-TCF4 trimeric complex decreased ferroptosis by inhibiting the function of ALOXE3." (PMID 38429254, 2024).
tumor (continued). "The top GRNs in primary tumors were TCF4, TAGLN2, FOXK1, and BHLHE41, whereas the top upregulated GRNs in recurrent tumor cells were FOXP2, FOXD1, SIX4, and HMGB1." (PMID 39711559, 2024). "To investigate the transcription pattern of the TCF/LEF family, we first compared the median levels of TCF7, TCF4, and TCF3 in normal and tumor tissues from pan-cancer patients in the TCGA cohort using FPKM and TPM expression values." (PMID 39205642, 2024). "TCF4 was included among the signature genes of NPC-like subprogram 2, emphasizing its regulatory function in tumor progression." (PMID 39363111, 2024). "Next, we examined TCF4 and TCF7 expressions in normal and tumor tissues across TCGA cancer types, respectively, using the RSEM expression value." (PMID 39205642, 2024). "In essence, FOXP4 emerges as a pivotal transcriptional target within the Wnt/β-catenin/TCF4 signaling axis, regulating the downstream transcription factor PTK7 and thereby fostering tumor proliferation, migration, and invasiveness." (PMID 38740744, 2024). "FOXP4 functions as a transcriptional target of Wnt/β-catenin/TCF4, facilitating PTK7 transcription and thereby fostering OV tumor development and advancement." (PMID 38740744, 2024). "Another YAP-transcriptional suppressor, Vestigial-like-4 (VGLL-4), has also recently emerged as a novel tumour suppressor in colon cancer by regulating both the YAP/TAZ and β-catenin-TCF4 complex." (PMID 38927266, 2024). "The MYC activator TCF4, which is part of the β-catenin complex that induces EMT and tumor invasion, was a top synthetic lethal hit with both GPS167 and 1C8." (PMID 38753413, 2024). "Overall, the expressions of TCF7, TCF4, and TCF3, which are members of the TCF/LEF family of proteins, are significantly different between normal and tumor samples, indicating the potential involvement of TCF/LEF in the occurrence and progression of cancers." (PMID 39205642, 2024). "Elevated ROS levels can shift the interaction of β-catenin from transcription factor 4 (TCF4) to forkhead box O3 (FOXO3a) and thus prevents tumorigenicity in vitro and tumor formation in vivo." (PMID 38017510, 2023). "It has been reported that oncogenic activation of KRAS/BRAF/MEK signaling stimulates Wnt/β-catenin pathway by β-catenin/TCF4 complex activation via Frizzled co-receptor LRP6 phosphorylation, which in turn promotes tumor growth and invasion." (PMID 37483610, 2023). "We compared the expression level of six frequently used markers for WNT activation (CTNNB1/beta-catenin, TCF1, TCF4, FZD7, MYC and CCND1) in normal and tumor tissue." (PMID 37149691, 2023). "Altogether, TCF4 was identified as a putative upstream regulator in controlling the expression of INTU and IFT88 in LUAD and UCEC tumor samples." (PMID 36084949, 2022). "Among these nine transcription factors, we found that only TCF4 expression was significantly downregulated in both LUAD and UCEC tumor samples." (PMID 36084949, 2022). "VHL is involved in HIF-1-alpha degradation, β-catenin/Tcf-4 signalling pathway and AKT activity inhibition therefore exerting a pivotal role as tumour suppressor." (PMID 35715818, 2022). "TCF4 was mutant in two MAPK-B tumors and one MAPK-C tumor, and involved in a fusion in a BRAFV600E-mutant MAPK-A tumor." (PMID 35440587, 2022). "Taken together, we provide in vivo evidence that demonstrates the role of TCF4 in promoting GPX4 expression, which results in the decrease of lipid peroxidation levels in tumors and facilitates tumor growth." (PMID 35534546, 2022). "Further analysis indicated that TCF4 expression in the cancer cells is correlated with the TAMs infiltration and M2 polarization in the CRC tumor tissue." (PMID 34580284, 2021). "Taking together, these data indicated that TCF4 expression in the CRC cells is essential for the TAMs recruitment and polarization and subsequent tumor growth in the mice models." (PMID 34580284, 2021).
tumor (continued). "We found that the protein expression of TCF4 and ENC1 in tumor tissues was largely consistent with those in cells." (PMID 34362881, 2021). "NSAIDs inhibit tumor DNA synthesis, modulate ER concentration and the COX, NF-κB, caspases and WNT (wingless and Int-1)-β-catenin-TCF4 (transcription factor 4) pathways, as well as glycogenesis, by inactivating 6-phosphofructose-1-kinase)." (PMID 34199169, 2021). "We focused on DNA (cytosine-5)-methyltransferase 1 (DNMT1), a DNA-binding enzyme responsible for the down-regulation of many tumor suppressor genes through hypermethylation of their promoter regions and a downstream effector of APC/β-catenin/TCF4 signaling." (PMID 32225105, 2020). "Similarly, a significant decrease in protein expression using IHC showed decreased TCF-4 protein expression in tumor tissue and adjoining mucosa compared to normal mucosa, which also corresponds to some important clinicopathological factors, including disease metastasis and tumor grade." (PMID 32265994, 2020). "In vivo, pre-let-7c inhibited while anti-let-7c potentiated tumor growth and WNT1 and TCF-4 were downregulated in xenografts with pre-let-7c." (PMID 32641854, 2020). "GATA6 competes with the β-catenin-TCF4 complex to bind to the enhancer elements of BMP4 to inhibit its expression, ultimately restricting BMP signalling to differentiate tumour cells in CRC." (PMID 32961708, 2020). "Increased GSK3β expression stimulated the β-catenin/TCF4/ZEB1/miR-200b network, which increased the downstream tumor stemness and EMT signals." (PMID 31754475, 2019). "This was also observed in vivo in HCT116 tumor xenograft model which showed a reduction in TCF4, β-catenin and LGR5 expression after γ-Mangostin treatment along with the reduced tumor volume and tumor weight." (PMID 31608135, 2019). "Mechanistic studies demonstrated that FOXO1-induced miR-200b expression through the GSK3β/β-catenin/TCF4 network-mediated stimulation of ZEB1, which reduced tumor stemness and the epithelial–mesenchymal transition (EMT) signal." (PMID 31754475, 2019). "TCF4, one of the most studied members of the TCL/LEF family, seems to have contradictory roles as both tumor-promoting and tumor-suppressing." (PMID 31382613, 2019). "Further more, we confirmed decreased expression of CTNNB1 downstream transcription factor TCF4 and target gene Cyclin D1 in METTL3 knockout HB cell Huh6 and tumor-bearing tissues of mice." (PMID 31870368, 2019). "Next, we performed immunohistochemical (IHC) staining for the expression of TCF4 and FZD6 in a separate cohort of 76 paraffin-embedded GBM tumours." (PMID 27698350, 2016). "To investigate the potential mechanism of Caco-2 cells and LoVo cells, we used PCR to examine the expression of mRNA in 19 genes including their difference in the tumor sample previously found and Axin1, LEF1, TCF4." (PMID 26214021, 2015). "IHC analysis of the tumour regions confirmed the reduced expression of TCF4, β-catenin and p68 as well as PCNA in the tumours generated with p68 knockdown cells when compared to the tumours generated with EV control cells." (PMID 25499975, 2014). "In the majority of matched pairs, OPN expression was decreased or unchanged in the liver metastasis compared with the primary tumour, whereas Ets1, Ets2, PEA3, Tcf4 and β-catenin were predominantly increased." (PMID 21343932, 2011). "Conversely, expression of each component of the OPN regulatory complex including Ets factors, Tcf4 and β-catenin was higher in CRLM than in primary tumours." (PMID 21343932, 2011).
tumor (continued). "Immunostains performed on consecutive serial histological sections showed that both TCF-4 and TTF-1 are expressed in the same areas within tumours." (PMID 21814573, 2011). "Both transcription factors were found mainly to be heterogeneously distributed throughout the tumours with expression of LEF-1 and TCF4 in cells of the invasive front in the majority of cases." (PMID 21092222, 2010). "TCF4 and LEF-1 expression was found to be heterogeneously distributed throughout the tumours, which is in support with the fact that individual tumours are organized hierarchically." (PMID 21092222, 2010). "Likewise, TCF4 expression is elevated in doxorubicin (DXR)-resistant OS cells and tissues, enhancing tumor progression by inhibiting the Wnt/β-catenin pathway." (PMID 40128298, 2025). "Notably, TRIB3 is key stress regulators in a variety of tumors because its C-terminal domain can interact with ubiquitin ligases and various other proteins to promote tumor progression, such as AKT1, β-catenin, SQSTM1, TRIM8, EGFR, and TCF4." (PMID 39881875, 2024). "A recent study found that the metabolites of BAs produced by microorganisms could attenuate the DNA‐binding activity of β‐catenin/TCF4 by activating FXR, and subsequently inhibit tumor proliferation and growth." (PMID 38665997, 2024). "In the tumour cells that reside post treatment, 40 candidates were found to have increased expression alongside enriched accessible binding motifs, including TP63, TCF4 and the well-defined regulator of OC cancer stem-cell differentiation, TWIST131." (PMID 39341888, 2024). "It has been reported thatLEF1, TCF4, and TCF7 areinvolved in the maturation and malignant transformation of thymocytes, developmentof natural killer and T cells, and through Wnt pathway, tumor infiltration andimmune evasion." (PMID 38100720, 2023). "Also several study mentioned miR-133a as a tumor suppressor miRNA which inhibit the GC growth and exert its effect via different target genes such as Sp1, IGF1R, TCF4 and etc42–44." (PMID 37061507, 2023). "This assumption is fostered by finding significantly lower expression levels of TCF4, whereas TCF4 is known to be in a direct interaction with LEF1 known as an interaction TCF/LEF, where overexpressed LEF1 leads to an enhanced tumor cell invasiveness and induces epithelial to mesenchymal transition." (PMID 38003292, 2023). "Moreover, we demonstrated novel TCF4 and ncRNA-involved mechanisms that contribute to the downregulation of INTU and IFT88 in LUAD and UCEC tumor samples." (PMID 36084949, 2022). "In addition, it has been shown that tumor growth is heavily dependent on glutamine and that glutamine deprivation increases DDIT3 expression through activating transcription factor-4 (ATF4)-mediated transcription." (PMID 36233241, 2022). "Reduction of the TCF4 protein level was recorded in both LUAD and UCEC tumor samples." (PMID 36084949, 2022). "We found that the β-catenin-TCF4-p300 complex occupies the CEGR/ALCD of GPC3 in the tumor sections of HBL patients, but not in the background regions." (PMID 36551548, 2022). "Moreover, the protein levels of LRP5, LRP6, TCF-4, and LEF1 in the tumor were also significantly down-regulated by AR decoction or oxaliplatin treatment in xenograft mice." (PMID 34991661, 2022). "Importantly, we found that expression of TCF4, CDC2 and CDC6 is up‐regulated in HCC tumour compared with non‐tumour tissue from GSE 37367, including over 400 human HCC samples." (PMID 33951279, 2021). "Immunostaining indicated that TCF4 + expression was related to LNM, serosal invasion, and PTNM stage, but not to patient gender, age, anatomical location, gross morphology, the degree of differentiation or tumor diameter." (PMID 32035486, 2020). "A total of 5 cases out of 60 tumor samples showed a band shift in exon 1 of the TCF4 gene, whereas no mobility shift was observed in normal and adjoining samples." (PMID 32265994, 2020).
tumor (continued). "With the exception of clonal Pdgfra and Nav3 insertions in one tumor, transposon insertions in MAPK/PI3K pathway and neurodevelopmental genes (including Nf1, Pten, Pik3r1, Ptprj, Sox6, Sox5, and Tcf4) were subclonal in these tumors, implying these were late evolutionary events." (PMID 32727536, 2020). "Furthermore, signals downstream of WNT/β-catenin, including the TCF4/ZEB1 signal, the tumor stemness pathway, and EMT, were shown to be downregulated in FOXO1-overexpressing NPC cells." (PMID 31754475, 2019). "In cells derived from the same tumor, we demonstrated that the prevalence of LEF1 (high β-catenin expressing cells) or TCF4 (low β-catenin expressing cells) as β-catenin partner for DNA binding, is associated to the expression of two distinct profiles of WNT-responsive genes." (PMID 27175588, 2016). "Adherent confluent Mel8 cells express higher level of WNT5a, TCF4 and VEGF and lower level of LEF1 at mRNA level than sub-confluent cells suggesting that these cells are prone to phenotype switch, simulating in vitro tumor spreading." (PMID 27175588, 2016). "Strikingly, the transcriptional regulator SPDEF was recently shown to act as a tumor metastasis suppressor in vivo and the multifactorial adaptor protein MAD2L2 (also known as MAD2B) was proposed to be involved in the TCF4-mediated epithelial-mesenchymal transdifferentiation." (PMID 26967245, 2016). "Because β-catenin/TCF-4 signalling plays a pivotal role in stem cell development, we examined whether AMA's ability to suppress the formation of tumor spheroids was through this pathway." (PMID 23840269, 2013). "Selected CRC target genes involved in apoptosis (BAX), tumor growth (TGFβRII), WNT pathway (AXIN2, TCF4, WISP3), DNA repair (ATM, ATR, BLM, BRCA1, BRCA2, DNAPKcs, MBD4, MRE11, MSH3, MSH6, RAD50, XRCC2) and PI3-kinase signaling (PTEN) were analyzed for mutations in MSI-positive HGG samples." (PMID 21637783, 2011). "Expression of HOXB13 is either lost or diminished in 26 out of 42 valid tumours (62%), while expression of TCF4 RNA is not correlated with HOXB13 expression." (PMID 15928669, 2005). "Thus, tumor development and progression in breast cancer may be regulated through axes such as SPRY4-IT1/miR-6882-3p/TCF7L2, LncCCAT1/miR-204/211/TCF4, and CASC15/miR-654-5p/MEF2D." (PMID 41181715, 2025). "To check whether β‐catenin is involved in miR‐378a‐3p‐elicited functional effects in HCC, we further analyzed the effect of blocking β‐catenin signaling via siRNA‐mediated knockdown of TCF4 or LEF1 on the proliferative, migratory, and invasive capacity of SMMC‐7721‐antagomiR‐378a‐3p tumor cells." (PMID 33634974, 2021). "We found two deleted regions shared by both tumor types in three out of the four cell lines H23R, A2780R, and OVCAR3R, but not in H460 cells, located on 18q21.2–18q21.31 and 18q21.32, affecting the genes RAB27B, CCDC68, TCF4, TXNL1, WDR7, and BOD1P; and genes ZNF532, SEC11C, GRP, respectively." (PMID 32224864, 2020). "Thus, targeting β-catenin-TCF4 interaction will have a significant impact on tumor cytotoxicity while remaining non-toxic to normal cells." (PMID 31608135, 2019). "This may explain why HOXB13 did not inversely correlate with the expression of TCF4 in patient tumour samples in our RNA analyses." (PMID 15928669, 2005). "TCF4 depletion does not impact CD11b+Ly6G+ neutrophils, CD16+CD56+ NK cells, and CD25+FOXP3+ T-reg cells population in the tumor microenvironment of syngeneic CRC liver metastases model." (PMID 34580284, 2021).